USP8 (ubiquitin specific peptidase 8)
Diseases named in the same sentence as USP8 in open-access papers (continued):
Sharing a sentence is not in itself a finding about the gene and the disease.
Salmonella Infections (2 papers, 2023). Infections with bacteria of the genus SALMONELLA. "Inhibition of USP8 was associated with a decrease in bacterial survival within macrophages, and it was found to play a distinct role in regulating autophagy during Salmonella infection." (PMID 37026055, 2023). "Moreover, USP8 inhibition was associated with an increased survival o THP-1 macrophages upon Salmonella infection." (PMID 37026055, 2023). "The effects of pharmacological inhibition of the identified deubiquitinase, USP8, were examined, including its impact on bacterial survival within macrophages and its role in autophagy regulation during Salmonella infection." (PMID 37026055, 2023). "We found that USP8 deubiquitinase is down-regulated during the Salmonella infection in human macrophages, which likely benefits the infected host since the pharmacological inhibition of this enzyme leads to the elimination of bacteria from the cells." (PMID 37026055, 2023). "The findings of this study suggest a novel role of USP8 in regulating autophagy flux, which restricts intracellular bacteria, particularly during Salmonella infection." (PMID 37026055, 2023). "One of the deubiquitinases identified was USP8, which was downregulated upon Salmonella infection." (PMID 37026055, 2023). "Hence, the effect of USP8 inhibition by DUBs-IN2 on autophagy during Salmonella infection and upon BafA treatment in THP-1 macrophages was tested by measuring p62 and LC3-II protein levels." (PMID 37026055, 2023). "Finally, a function of one of these deubiquitinases, USP8 was evaluated in the host response to Salmonella infection." (PMID 37026055, 2023). "Mass-spectrometry-based quantification of active deubiquitinases established that USP8 was downregulated during Salmonella infection but not affected by Y. enterocolitica infection." (PMID 37026055, 2023). "Also, USP8 inhibition led to an increase in LC3-II during Salmonella infection but not upon BafA-mediated inhibition of autophagy." (PMID 37026055, 2023). "Finally, since Salmonella infection leads to an increase in pro-inflammatory TNF-α increase, we also tested whether this cytokine is affected by USP8 inhibition." (PMID 37026055, 2023).
vitiligo (2 papers, 2023 to 2024). Generalized well circumscribed patches of leukoderma that are generally distributed over symmetric body locations and is due to autoimmune destruction of melanocytes. "Consistent with the bioinformatic analysis results, GABARAPL2 and USP8 mRNA levels were raised in vitiligo lesions, whereas the mRNA levels of RELA, TBC1D17, and SP1 were decreased." (PMID 37287971, 2023). "Then, five mitophagy hub genes (GABARAPL2, SP1, USP8, RELA, and TBC1D17) were identified using two machine learning algorithms, and these genes showed high diagnostic specificity for vitiligo." (PMID 37287971, 2023). "The AUC values of hub genes were high in the combined dataset (GABARAPL2, AUC=0.988; USP8, AUC=0.94; RELA, AUC=0.927; SP1, AUC=0.894; and TBC1D17, AUC=0.927), implying that the five hub genes have high specificity for vitiligo and could be used as vitiligo diagnostic biomarkers." (PMID 37287971, 2023). "Furthermore, GABARAPL2, RELA, TBC1D17, and USP8, except of SP1, are implicated in cellular responses to stress and external stimuli; External stimuli, such as stress and oxidative stress, are vital factors in the etiology of vitiligo." (PMID 37287971, 2023). "The results showed elevated GABARAPL2 and USP8 and decreased RELA, SP1, and TBC1D17 in vitiligo compared to healthy controls, which were consistent with bioinformatic analysis results." (PMID 37287971, 2023). "Through LASSO regression analysis and the random forest algorithm, we screened five mitophagy-related hub DEGs (GABARAPL2, USP8, RELA, SP1, and TBC1D17) in vitiligo." (PMID 37287971, 2023).
acral melanoma (1 paper, 2022). "In the Cancer Genome Atlas, we found one case of acral melanoma (TCGA-ER-A19T-01) harboring a strong focal amplification on chromosome 15 (orthologous to canine chromosome 30) encompassing the candidate oncogenes SPPL2A, USP8, TRPM7, and GABPB1." (PMID 35053440, 2022).
atherosclerosis (1 paper, 2024). A disease characterized by the build-up of fatty material and calcium deposition in the arterial wall resulting in partial or complete occlusion of the arterial lumen. "USP8, altered in our data, is important for endosomal trafficking in atherosclerosis and is induced in the presence of growth arrest during cell–cell contact and is also important in RAS signaling and Wnt pathway regulation." (PMID 39120300, 2024).
autism (1 paper, 2020). Persistent deficits in social interaction and communication and interaction as well as a markedly restricted repertoire of activity and interest as well as repetitive patterns of behavior. "From the single gene annotation analysis, it can be seen that the abnormalities of MED13, POU3F2, and USP8 have been confirmed to induce autism." (PMID 32273901, 2020). "Therefore, USP8 and SHANK3 synergistically affect the development of autism." (PMID 32273901, 2020).
autosomal recessive spastic paraplegia type 59 (1 paper, 2025). "USP8 may be closely associated with a variety of diseases, including pituitary adrenocorticotropic hormone-secreting adenomas, pituitary-dependent Cushing's disease, esophageal squamous cell carcinoma, hereditary spastic paraplegia, and autosomal recessive spastic paraplegia type 59." (PMID 40355913, 2025).
chronic obstructive pulmonary disease (1 paper, 2025). A chronic and progressive lung disorder characterized by the loss of elasticity of the bronchial tree and the air sacs, destruction of the air sacs wall, thickening of the bronchial wall, and mucous accumulation in the bronchial tree. "Additionally, several studies indicate that USP8 confers ferroptosis resistance through β-catenin stabilization or OGT-SLC7A11 axis in HCC, and inhibits ferroptosis via regulating OTUB1-SLC7A11 pathway in chronic obstructive pulmonary disease (COPD)." (PMID 40862294, 2025).
Cirrhosis (1 paper, 2024). A chronic disorder of the liver in which liver tissue becomes scarred and is partially replaced by regenerative nodules and fibrotic tissue resulting in loss of liver function. "Recently, it has been reported that USP8 expression is downregulated in hepatic macrophages of patients with cirrhosis, possibly implicating the link between aberrant signaling caused by endosomal stress and pathology." (PMID 38180476, 2024).
colitis (1 paper, 2025). Inflammation of the colon. "Mice with a T cell-specific inactivation of USP8 (Usp8f/fCd4Cre) develop colitis, which is mediated by CD8+ γδT cells in concert with dysfunctional TRegs." (PMID 39404738, 2025). "Notwithstanding these caveats, we speculate that the disequilibrium imposed on CTLA4 following USP8 deletion may contribute to the colitis phenotype." (PMID 39404738, 2025).
colon adenocarcinoma (1 paper, 2022). "Moreover, results from our bioinformatic analysis demonstrated that most of the genes in the MHC-I pathways are significantly upregulated in lung or colon adenocarcinoma patients with low USP8 compared with high USP8 expression." (PMID 35361799, 2022).
colon cancer (1 paper, 2022). "Consistent with results from syngeneic mouse colon tumor models, the USP8 inhibitor combined with anti-PD-L1 antibody significantly suppressed tumor development in KP mice, evidenced by the reduced tumor sizes and areas, compared to either each agent alone or control group." (PMID 35361799, 2022). "Together, our results demonstrate that the combined therapy with the USP8 inhibitor, DUBs-IN-2, and anti-PD-1/PD-L1 has similar efficacy in both lung and colon cancer tumor models, indicating that the mechanism of this study should be suitable for both NSCLC and colon cancers." (PMID 35361799, 2022).
cutaneous melanoma (1 paper, 2022). A primary melanoma arising from atypical melanocytes in the skin. "Interestingly, USP8 knockdown suppressed cell growth, survival, and migration in cutaneous melanoma." (PMID 35053440, 2022).
diabetes (1 paper, 2021). "Afterwards, the same group has identified that H2S promotes the S-sulfhydration of ubiquitin specific peptidase 8 (USP8) and muscle RING finger-1 (MuRF1), thereby preventing cardiac structural injury in diabetes." (PMID 34764865, 2021).
diabetic cardiomyopathy (1 paper, 2020). Diabetic cardiomyopathy is a disorder of the heart muscle in people with diabetes. "Taken together, these findings further support a model whereby the USP8-mediated deubiquitination of parkin is critical for mitophagy, which ameliorates mitochondrial morphology in diabetic cardiomyopathy." (PMID 32257541, 2020). "Regardless of the precise mechanism, our work uncovers a novel layer of the exogenous H2S-mediated regulation of diabetic cardiomyopathy through the S-sulfhydration of USP8, critical for parkin-dependent mitophagy." (PMID 32257541, 2020).
endometrioid ovarian carcinoma (1 paper, 2022). "Besides, a synergistic interaction between cisplatin and caffeic acid phenethyl ester, capable to inhibit USP8, has been observed in endometrioid ovarian carcinoma cells." (PMID 36578788, 2022).
endothelial dysfunction (1 paper, 2023). In vascular diseases, endothelial dysfunction is a systemic pathological state of the endothelium (the inner lining of blood vessels) and can be broadly defined as an imbalance between vasodilating and vasoconstricting substances produced by (or acting on) the endothelium. "The therapeutic effects of melatonin on endothelial dysfunction in sepsis were mediated by upregulating USP8 expression and inhibiting NICD degradation, maintaining the stability of Notch signaling." (PMID 37205094, 2023).
HIV-1 infection (1 paper, 2021). The type species of lentivirus and the etiologic agent of acquired immunodeficiency syndrome (AIDS). "To examine the possible effect of USP8 on HIV-1 infection, we first co-expressed increasing amounts of USP8 with HIV-1 (NL4-3)." (PMID 34630422, 2021). "In both H9 and Jurkat CD4+ T cells, HIV-1 infection resulted in depletion of USP8 proteins significantly." (PMID 34630422, 2021). "HIV-1 infection could interfere with T-cell function by disturbing the expression of USP8 or its interaction with Gads5." (PMID 34630422, 2021). "The deubiquitination enzyme USP8 is a human T cell-specific factor regulating T-cell maturation and functions, and CD4+ T cells are primary targets of HIV-1 infection." (PMID 34630422, 2021). "Meanwhile, both mRNA and protein expression levels of USP8 were significantly downregulated during HIV-1 infection in T cells, which indicated that HIV-1 has evolved new antagonisms against USP8." (PMID 34630422, 2021).
Hydrocephalus (1 paper, 2018). Hydrocephalus is an active distension of the ventricular system of the brain resulting from inadequate passage of CSF from its point of production within the cerebral ventricles to its point of absorption into the systemic circulation. "Cystic kidney, hydrocephalus, and microphthalmia, which were observed in usp8 KO zebrafish, are also accompanied in both Joubert and Meckel syndromes." (PMID 29472535, 2018).
Hyperglycemia (1 paper, 2020). An increased concentration of glucose in the blood. "Our results showed that hyperglycemia and hyperlipidemia decreased the translocation of parkin in the mitochondrial outer membrane and decreased the interaction between USP8 and parkin." (PMID 32257541, 2020). "Our results showed that exogenous H2S could result in the S-sulfhydration of USP8 under hyperglycemia and hyperlipidemia, leading to the enhanced interaction of USP8 with parkin and the translocation of parkin into mitochondria." (PMID 32257541, 2020). "Therefore, we speculated that exogenous H2S likely promoted the USP8-mediated deubiquitination of parkin that regulated mitochondrial function via promoting mitophagy under hyperglycemia and hyperlipidemia." (PMID 32257541, 2020).
lymphopenia (1 paper, 2024). Reduction in the number of lymphocytes. "Perhaps USP8 and MEN1 are the key genes between cortisol regulation and lymphopenia, which needs further confirmation." (PMID 38376054, 2024).
myxofibrosarcoma (1 paper, 2024). A malignant fibroblastic neoplasm arising from the soft tissue. "In fact, PDGFRA::USP8 gene fusion was previously reported from a primary cardiac myxofibrosarcoma in a 5 year old boy." (PMID 38401149, 2024).
neuroendocrine tumors (1 paper, 2024). "Characterization of USP8 mutations in neuroendocrine tumors has shown that they promote oncogenic transformation through the activation of EGF receptor signaling." (PMID 39456581, 2024). "Somatic activating mutations in USP8 located between the amino acids 713 and 720 have been identified in (ACTH)-secreting neuroendocrine tumors." (PMID 39456581, 2024).
oral mucositis (1 paper, 2026). Inflammation of the mucous membranes of any of the structures in the mouth. "As a crucial regulator of EGFR sorting and degradation, USP8 inhibition potently suppresses EGFR signaling (a promising strategy for EGFR-driven cancers) but may simultaneously induce epidermal and gastrointestinal toxicities, such as rash, itching, dry skin, oral mucositis, diarrhea, and anorexia." (PMID 41565619, 2026).
oral squamous cell carcinoma (1 paper, 2025). "Whilst no DUBs have previously been reported to regulate KIFC1, candidates from genome-wide screens for centrosome clustering regulators in Drosophila or oral squamous cell carcinoma, included orthologs of USP8 (CG5798) and USP43 (CG30421) and the pseudo-DUB USP54." (PMID 39789388, 2025).
osteoarthritis (1 paper, 2025). A noninflammatory degenerative joint disease occurring chiefly in older persons, characterized by degeneration of the articular cartilage, hypertrophy of bone at the margins and changes in the synovial membrane. "Therefore, our research supports the notion that USP8 may influence the onset and progression of osteoarthritis." (PMID 39932908, 2025).
Ovarian Tumour (1 paper, 2015). "These 33 enzymes represent >1/3 of all known human DUBs, and they include members of all four major DUB families—20 USPs (including CYLD, USP14 an USP8), 8 Ovarian Tumour (OTU) deubiquitinases (including Trabid and Cezanne), 3 ubiquitin C-terminal hydrolases (UCHs) and 2 JAMM metalloproteases." (PMID 25907794, 2015).
Sepsis (1 paper, 2023). Sepsis is defined as life-threatening organ dysfunction caused by a dysregulated host response to infection. "Although emerging evidence has implicated a role for m6A modification in sepsis, whether m6A modification directly associates with Usp8 requires further exploration." (PMID 37205094, 2023). "We also observed that melatonin mitigated sepsis-induced EC injury by upregulating USP8, thus stabilizing NICD, providing scientific support for the application of melatonin to treat sepsis." (PMID 37205094, 2023). "Melatonin, however, upregulated USP8 expression, thus maintaining the stability of NICD and Notch signaling, which ultimately reduced EC injury in our sepsis model and elevated the survival rate of septic mice." (PMID 37205094, 2023).
skin inflammation (1 paper, 2022). "Transmembrane protein 79 (TMEM79, a predisposition gene for AD) can specifically inhibit ubiquitin-specific peptidase 8 deubiquitination, and its deficiency shows more susceptible to developing skin inflammation, compromised barrier function, and spontaneous dermatitis." (PMID 35874824, 2022).
spindle cell neoplasm (1 paper, 2024). A benign or malignant neoplasm characterized by the presence of neoplastic spindle cells. "We report a case of a pediatric primary cardiac spindle cell neoplasm with a PDGFRA::USP8 gene fusion in the right ventricle, arising from the inlet part of the ventricular septum." (PMID 38401149, 2024). "In summary, we report a case of pediatric primary cardiac unclassified spindle cell neoplasm with a very rare PDGFRA::USP8 gene fusion." (PMID 38401149, 2024). "Pathology revealed an unclassified spindle cell neoplasm with a PDGFRA::USP8 gene fusion." (PMID 38401149, 2024). "We report a case of a primary cardiac spindle cell neoplasm with concerning histological features and a rare PDGFRA::USP8 gene fusion in a 3 year old boy." (PMID 38401149, 2024).
triple-negative breast carcinoma (1 paper, 2026). An invasive breast carcinoma which is negative for expression of estrogen receptor (ER), progesterone receptor (PR), and human epidermal growth factor receptor 2 (HER2). "The findings indicate a connection between USP8 and Hippo signaling pathway activity in triple-negative breast cancer." (PMID 41565619, 2026).
type 2 diabetes mellitus (1 paper, 2024). A type of diabetes mellitus that is characterized by insulin resistance or desensitization and increased blood glucose levels. "Specifically, in cardiac dysfunction amelioration in type 2 diabetes mellitus (T2DM), the S‐sulfhydration of USP8 enhances its deubiquitination of parkin, which facilitates parkin's translocation into mitochondria and mitigates oxidative stress and mitochondrial apoptosis." (PMID 39678489, 2024).